LNCMB2 (lncRNA MYC regulated medulloblastoma associated 2)
Gene: Long non-coding RNA gene on chromosome 8 (37,326,538 to 37,331,991, reverse strand). Ensembl gene ENSG00000253123.
Diseases named in the same sentence as LNCMB2 in open-access papers:
LNCMB2 is named in the same sentence as 1 disease in open-access papers, as found by Europe PMC text mining. Sharing a sentence is not in itself a finding about the gene and the disease. The quoted sentences say what the papers report.
cancer (1 paper, 2021). A tumor composed of atypical neoplastic, often pleomorphic cells that invade other tissues. "Next, we addressed the function of lncMB2 and lncMB1. lncMB2 is a predominantly nuclear transcript, whose proximal genes ZNF703 and ADGRA2, mapping about 360 Kb and 460 Kb apart from lncMB2 locus (AC091182.1), respectively, are both related to cancer." (PMID 34359754, 2021).